RNU1-18P (RNA, U1 small nuclear 18, pseudogene)
Gene: Small nuclear RNA gene on chromosome 6 (122,211,648 to 122,211,811, forward strand). Ensembl gene ENSG00000199932.
Homologues: Orthologues: chimpanzee U1 (98% identical), pig U1 (85% identical). Paralogues in human: RNU1-1 (89% identical), RNU1-2 (89% identical), RNU1-27P (89% identical), RNU1-28P (89% identical), RNU1-3 (89% identical), RNU1-4 (89% identical), RNU1-89P (89% identical), RNVU1-18 (89% identical), RNVU1-29 (89% identical), RNVU1-31 (89% identical), U1 (89% identical), RNVU1-28 (88% identical), and 134 more.